PIM3 (Pim-3 proto-oncogene, serine/threonine kinase)
Diseases named in the same sentence as PIM3 in open-access papers (continued):
Sharing a sentence is not in itself a finding about the gene and the disease.
hepatoblastoma (6 papers, 2018 to 2023). Hepatoblastoma (HB) is a malignant hepatic tumor and is the most common pediatric liver cancer. "Prior studies in our lab have shown PIM3 to be of particular importance in hepatoblastoma thus we began by evaluating the effects of PIM3 knockdown on HLM_2 cell proliferation." (PMID 38203596, 2023). "In primary hepatoblastoma, PIM3 correlates with worse patient prognosis, increased tumor cell proliferation, motility, stemness, and drug resistance." (PMID 38203596, 2023). "Marayati and colleagues demonstrated that the stable overexpression of PIM3 in hepatoblastoma cell lines led to increased resistance to cisplatin." (PMID 35892829, 2022). "The knockdown of PIM3 with siRNA or treatment with the pan-PIM inhibitors AZD1208 or PIM447 resulted in decreased hepatoblastoma cell viability, motility, and attachment-independent growth." (PMID 35892829, 2022). "They showed that PIM3-overexpressing hepatoblastoma cells formed tumorspheres more readily than empty vector control cells, which is a characteristic of SCLCCs." (PMID 35892829, 2022). "PIM3 is the specific family member believed to play a role in hepatoblastoma tumorigenesis and tumor maintenance." (PMID 35892829, 2022). "In the current study, we developed cisplatin-resistant hepatoblastoma xenograft models and showed that cisplatin-resistant cells are enriched for SCLCCs and have higher PIM3 expression." (PMID 33727604, 2021). "We showed that PIM3 overexpression increased cell surface expression of CD133 and mRNA abundance of stemness markers, and was associated with cisplatin insensitivity in hepatoblastoma cells." (PMID 33727604, 2021). "We have previously demonstrated that Proviral Integration site for Moloney murine leukemia virus (PIM) kinases, specifically PIM3, play a role in hepatoblastoma cell proliferation and tumor growth and maintain the SCLCC phenotype." (PMID 33727604, 2021). "We previously demonstrated that PIM3 phosphorylated BAD in hepatoblastoma impeding apoptosis and promoting tumorigenesis." (PMID 33727604, 2021). "Pim3 is correlated with enhanced tumor growth and cell survival and its overexpression can enhance the proliferation of hepatoblastoma cells." (PMID 32245399, 2020). "PIM3 was specifically targeted with siRNA and resulted in decreased proliferation and cell migration, substantiating the importance of PIM3 in hepatoblastoma." (PMID 29854306, 2018). "The expression of PIM kinases (PIM1, PIM2, and PIM3) was evaluated in the long-term passaged human hepatoblastoma cell line, HuH6, and the human hepatoblastoma PDX cell line, COA67, by immunoblotting." (PMID 29854306, 2018). "Parameters including cell survival, proliferation, motility, and apoptosis were assessed in human hepatoblastoma cells following PIM3 knockdown with siRNA or treatment with the PIM inhibitor AZD1208." (PMID 29854306, 2018). "PIM3 expression was found to be present in human hepatoblastoma specimens by immunohistochemistry and less expression was observed in normal human liver tissue." (PMID 29854306, 2018). "In addition, PIM inhibition combined with cisplatin synergistically decreased tumor growth in vivo leading us to believe that PIM3 plays a role in mediating chemoresistance to cisplatin hepatoblastoma by maintaining the SCLCC phenotype." (PMID 33727604, 2021). "Since patient derived xenografts (PDXs) may more closely represent the human condition, PIM3 inhibition was evaluated using a hepatoblastoma PDX (COA67)." (PMID 29854306, 2018). "We can speculate the role of PIM3 in mediating cisplatin resistance in hepatoblastoma." (PMID 33727604, 2021). "Immunoblotting demonstrated increasing PIM3 expression in both HuH6 and COA67 with increasing insensitivity to cisplatin, indicating that PIM3 expression correlates with cisplatin resistance in hepatoblastoma." (PMID 33727604, 2021).
hepatoblastoma (continued). "The enlarged image reveals the PIM3 staining of hepatoblastoma cells in contrast with the lack of staining in the peri-portal connective tissue of the liver (black arrow)." (PMID 29854306, 2018). "We hypothesized that PIM kinases, specifically PIM3, would play a role in hepatoblastoma tumorigenesis and that PIM kinase inhibition would affect hepatoblastoma in vitro and in vivo." (PMID 29854306, 2018). "Since PIM3 expression was increased in the cisplatin-resistant cells, we sought to determine whether combining the pan-PIM inhibitor, AZD1208, to cisplatin would more effectively decrease proliferation of cisplatin-resistant hepatoblastoma cells." (PMID 33727604, 2021). "While these data suggested that PIM3 may be the PIM kinase family member that contributes most significantly to hepatoblastoma tumorigenicity, there are currently no PIM3-specific drugs available for clinical use." (PMID 29854306, 2018). "Further, the expression of PIM3 by IHC in normal liver parenchyma was nearly undetected, leading us to hypothesize that PIM3 inhibition will be cytotoxic to hepatoblastoma cells but not normal liver cells." (PMID 29854306, 2018).
glioblastoma (5 papers, 2012 to 2024). The most malignant astrocytic tumor (WHO grade IV). "PIM3 knockdown effectively suppressed the development of glioblastoma cells transplanted subcutaneously in vivo." (PMID 38339286, 2024). "In human glioblastoma cells (U87MG) with activated mTORC1 signaling downstream of PTEN loss, PIM3 transcript levels were increased upon mTORC1 inhibition." (PMID 29170467, 2017). "PIM3 is among the oncogene targets of miR-124 in glioblastoma and it promotes tumor cell growth through modulating cell cycle." (PMID 26041995, 2015). "Furthermore, PIM3 knockdown with shRNA resulted in decreased proliferation, cell cycle arrest in the G0/G1 phase, and enhanced apoptosis in glioblastomas." (PMID 38339286, 2024). "PIM3, on the other hand, is usually observed in adenocarcinomas of the pancreas, colon, and liver, as well as in melanoma, glioblastoma, and TNBC, and has been reported to play a significant role in cell proliferation, cell cycle regulation, and apoptotic signaling." (PMID 38339286, 2024). "Moreover, a significant increase of PIM3 mRNA expression was detected in the glioblastoma stem cells tested, compared to neural stem cells, further supporting the idea that miR-124 represses PIM3 expression." (PMID 22558405, 2012). "Furthermore, using the Targetscan algorithm, we predicted oncogenes NRAS and PIM3 as putative target genes of miR-124, one of the down-regulated miRNAs in glioblastoma stem cells." (PMID 22558405, 2012).
leukemia (4 papers, 2014 to 2023). A malignant (clonal) hematologic disorder, involving hematopoietic stem cells and characterized by the presence of primitive or atypical myeloid or lymphoid cells in the bone marrow and the blood. "A role for Myc in cooperating with Pim-3 in the develop of B- or T-cell lymphomas/leukemias has only been shown indirectly." (PMID 36694243, 2023). "PIM2 and PIM3 did not appear to be correlated with ABC protein expression, although these studies focused on leukemia and myeloma, in which PIM1 is known to play a larger role." (PMID 33727604, 2021).
lymphoma (4 papers, 2011 to 2024). A malignant (clonal) proliferation of B- lymphocytes or T- lymphocytes which involves the lymph nodes, bone marrow and/or extranodal sites. "The proviral insertion in murine (PIM) lymphoma proteins are a serine/threonine kinase family composed of three isoformes: Pim-1, Pim-2 and Pim-3." (PMID 25491234, 2014). "To our surprise we find that the most highly expressed Pim kinase in these lymphomas is Pim-3, and that Pim3 is a Myc target gene." (PMID 21646687, 2011). "Accordingly, lymphomas arising in Myc-transgenic mice and Burkitt lymphoma cell lines exhibit elevated levels of Pim-3." (PMID 21646687, 2011). "Taken together, our results confirm that E-box 1 in the PIM3 locus is a functional target of Myc-mediated transcription in both human and mouse lymphoma cells." (PMID 21646687, 2011). "Taken together, the data indicate that Pim-3 is the main Pim kinase overexpressed in Myc-induced lymphomas from mice and patients whereas Pim-1 and Pim-2 are more sporadically overexpressed." (PMID 21646687, 2011). "To assess if Myc directly regulates PIM3 in human cells we used the P493-6 lymphoma cell line, which has a tetracycline (Tet) regulatable Myc cassette, which is silent in the presence of tetracycline." (PMID 21646687, 2011). "Moreover, immunohistochemistry analysis of Pim-3 expression in mantle cell lymphoma (MCL), follicular lymphoma (FL), diffuse large cell B-cell lymphoma (DLCBL) and BL showed that BL is the lymphoma-type that exhibits the highest Pim-3 expression." (PMID 21646687, 2011). "Interestingly, elevated Pim3 mRNA and Pim-3 protein were seen not only in tumors but also in B cells harvested from 4-6 week old precancerous mice with no signs of lymphoma." (PMID 21646687, 2011).
melanoma (4 papers, 2016 to 2024). A malignant, usually aggressive tumor composed of atypical, neoplastic melanocytes. "In a tumor-bearing mouse model, sh-PIM3 dramatically reduced lung metastasis of B16F10 melanoma cells." (PMID 38339286, 2024). "They silenced PIM3 using a short hairpin RNA (sh-PIM3) in a B16F10 melanoma cell line and discovered that sh-PIM3 decreased B16F10 cell migration and invasion in vitro." (PMID 38339286, 2024). "46% and 16% of Pecam1+ ECs were positive for both Pim3 and Bcl3 or Pim3 and Inhbb, respectively, indicating tumor-induced upregulation of the rCaps 6 h after melanoma injection." (PMID 39627185, 2024). "Here, the authors use single-cell RNA-seq to examine the reprogramming of lung ECs in mouse models of melanoma metastasis, revealing that PIM3 protects capillary integrity and that its inhibition increases vascular leakage and metastatic colonisation." (PMID 39627185, 2024). "Interestingly, Inhbb and Bcl3 showed low expression in the control lungs, while Pim3, Inhbb and Bcl3 were enriched in the metastatic lungs, especially in the vicinity of melanoma cells when compared to regions distant to melanoma cells." (PMID 39627185, 2024). "Our present study used an ssRNA-sh-Pim-3 dual-function vector to treat melanoma and showed that this therapeutic strategy can subvert tumor-induced immunosuppression by inducing activation of both NK and CD8+ T cells and reducing the percentages of Tregs and MDSCs in the tumor microenvironment." (PMID 31849942, 2019). "Analysis of B16-F10 metastatic mouse lungs by sorting PECAM1+ ECs, CellTracker+ melanoma and PECAM1-CellTracker- cell populations showed significantly higher levels of Pim3 in ECs, as compared to the other lung cell populations." (PMID 39627185, 2024). "Collectively, these results indicate that silencing of Pim-3, particularly by the ssRNA-Pim-3-shRNA dual-function vector, significantly promotes apoptosis and inhibits the proliferation of B16F10 melanoma cells in vitro." (PMID 31849942, 2019). "We observed the expression of PIM1 and PIM2 in all melanoma samples, while PIM2 and PIM3 levels were most elevated in samples expressing lower PIM1 levels." (PMID 27448973, 2016). "To confirm PIM kinases as valid targets for melanoma patients and to assess expression variability, we stained human melanoma tissue for PIM1, PIM2, PIM3." (PMID 27448973, 2016). "PIM3 promotes the phosphorylation of STAT3, which stimulates the production of Slug, Snail, and ZEB1, thereby enhancing EMT-related alterations and inducing melanoma migration and invasion." (PMID 38339286, 2024). "Using knockdown studies, we showed that PIM1 contributes to melanoma cell proliferation and tumor growth in vivo; however, the presence of PIM2 and PIM3 could also influence the outcome." (PMID 27448973, 2016).
colon cancer (3 papers, 2015 to 2024). "When PIM1 was inhibited, PIM2 expression increased across different cancer types generally, and Pim-3 was reported to be aberrantly expressed in colon cancer." (PMID 25749522, 2015). "Furthermore, in human colon cancer tissues, PIM3 co-localized with Bad in all cases and with phospho-Ser Bad in the majority of cases." (PMID 38339286, 2024).
liver cancer (3 papers, 2023 to 2024). An epithelial or non-epithelial malignant neoplasm that arises from the liver. "In summary, we believe that overexpression of Pim-3 upregulation caused by underexpression of miR-936 promotes t sorafenib resistance in liver cancer, partially by inhibiting ferroptosis." (PMID 39507762, 2024). "Most importantly, the aberrant expression of Pim-3 caused by miR-936 deficiency accelerated the development of sorafenib resistance by inhibiting cell ferroptosis in liver cancer." (PMID 39507762, 2024). "Similarly, Pim-3 expression was positively associated with sorafenib resistance in liver cancer cells." (PMID 39507762, 2024). "In the present study, it was demonstrated for the first time that Pim-3 can promote sorafenib resistance in liver cancer." (PMID 39507762, 2024). "Pim-3 expression was also particularly greater in sorafenib-resistant liver cancer cell lines Huh7/SOR and HepG2/SOR compared with the corresponding parental cells." (PMID 39507762, 2024). "Herein, we demonstrated that Pim-3 endowed liver cancer patients with insensitivity to sorafenib and predicts an undesirable prognosis in liver cancer patients receiving sorafenib treatment." (PMID 39507762, 2024). "The key nodes in the miR-936/Pim-3/ANKRD18A/Src/NRF2 axis that regulate ferroptosis resistance in liver cancer should also be further determined." (PMID 39507762, 2024). "We showed that upregulation of the provirus-integrating site for Moloney murine leukemia virus 3 (Pim-3) predicted poor response and unsatisfactory prognosis in sorafenib-treated liver cancer patients." (PMID 39507762, 2024). "Here, credible targets involved in Pim-3-induced sorafenib resistance in liver cancer were identified with mRNA microarray analysis." (PMID 39507762, 2024). "However, much less is known about the role of Pim-3 in promoting sorafenib resistance in liver cancer." (PMID 39507762, 2024). "Pim-3 can be regarded as a target in the treatment of sorafenib-resistant liver cancer." (PMID 39507762, 2024). "To date, the clinical relevance of Pim-3 expression in liver cancer patients undergoing sorafenib therapy remains unclear." (PMID 39507762, 2024). "Furthermore, microRNA-936 (miR-936) targeted the 3’-noncoding region (3'-UTR) of Pim-3 but exhibited lower expression in sorafenib-resistant liver cancer cells than in their parental cells." (PMID 39507762, 2024). "Therefore, Pim-3, whose expression was positively correlated with low a miR-936 level, suppressed ferroptosis in sorafenib-resistant liver cancer cells by accelerating the activation of the ANKRD18A/Src/NRF2 pathway." (PMID 39507762, 2024). "Next, we aimed to determine whether extreme Pim-3 expression induced by a low miR-936 level can mediate sorafenib resistance in liver cancer." (PMID 39507762, 2024). "In addition, it is reasonable to conclude that Pim-3 upregulation mediated by a low miR-936 expression promotes sorafenib resistance in liver cancer by inhibiting ferroptosis, in which the activation of the ANKRD18A/Src/NRF2 pathway, especially the transcriptional activity of NRF2, is essential." (PMID 39507762, 2024). "There was also a negative correlation between Pim-3 and miR-936 expression in liver cancer tissues." (PMID 39507762, 2024). "Moreover, the elevated expression of Pim-3, resulting from the absence of miR-936 enhances sorafenib resistance in liver cancer by inhibiting cell ferroptosis." (PMID 39507762, 2024).
ovary cancer (3 papers, 2014 to 2022). "MACC1 expression has been shown to correlate with PIM3 expression and overexpression of PIM3 in ovary cancer cells increased MACC1 mRNA and protein expression." (PMID 33946744, 2021).
B cell lymphomas (2 papers, 2011 to 2015). "This is the first time Myc has been implicated in regulation of a Pim kinase family member and it explains the high levels of Pim-3 found in Myc overexpressing mouse B cell lymphomas and human BL." (PMID 21646687, 2011).
diffuse large B-cell lymphoma (2 papers, 2011 to 2024). "AZD4573 could downregulate multiple oncoproteins (MYC, Mcl-1, JunB, PIM3) and deregulate PI3K pathways in diffuse large B-cell lymphoma (DLBCL)." (PMID 38566153, 2024).
liposarcoma (2 papers, 2019 to 2021). A usually painless malignant tumor that arises from adipose tissue. "In this study, we report for the first time that AZD1208 inhibits the growth of 93T449 human liposarcoma cells through Pim-3, 4EBP-1, mTOR, S6, eIF-2α, STAT-3 and AMPK." (PMID 30654529, 2019).
lung carcinoma (2 papers, 2020 to 2023). "As ZNF322A has been suggested to transcriptionally regulate expression of PIM3, qRT-PCR and immunoblotting were performed on A549 lung cancer cells with ZNF322A perturbation." (PMID 32576196, 2020).
myeloid leukemia (2 papers, 2014 to 2018). A clonal proliferation of myeloid cells and their precursors in the bone marrow, peripheral blood, and spleen. "Transplantation of murine bone marrow co-expressing MYC and PIM1, PIM2 or PIM3 caused rapid and uniformly lethal myeloid leukemia." (PMID 25238262, 2014). "Consistent with this, a recent study has revealed that all three Pim kinases, including Pim-3, activated the indistinguishable downstream signaling cascades, protected FL5.12 cells from IL-3 withdrawal, and cooperated with Myc to induce myeloid leukemia in mice." (PMID 29507660, 2018).
neuroblastoma (2 papers, 2019 to 2023). Neuroblastoma (NB) is the most common solid, extracranial childhood tumor. "PIM1 and PIM3 were expressed in neuroblastoma cell lines and PDX‐derived cell cultures." (PMID 31310053, 2019).
Obesity (2 papers, 2018 to 2024). Accumulation of substantial excess body fat. "For SOCS3, CISH, PIM3 (Pim-3 proto-oncogene, serine/threonine kinase), and KLF4 (Kruppel-like factor 4), obesity was associated with decreased methylation and increased gene expression, while for HRASLS2, obesity was associated with decreased methylation and decreased gene expression." (PMID 29312471, 2018).
sarcoma (2 papers, 2014 to 2024). A usually aggressive malignant neoplasm of the soft tissue or bone. "PIM3 was constitutively expressed in SW480 sarcoma cells, and its inhibition by short hairpin RNA induced apoptosis." (PMID 38339286, 2024). "We showed that the absence of Pim2 and Pim3 greatly reduced sarcoma growth and that the extent of this reduction was similar to that observed in the absence of all three isoforms." (PMID 24860787, 2014).
Sepsis (2 papers, 2022 to 2025). Sepsis is defined as life-threatening organ dysfunction caused by a dysregulated host response to infection. "More patients with sepsis, positive respiratory pathogens, higher PIM3 and PELOD2 scores, and higher IAG were in higher-risk phenotype group, which had worse outcomes." (PMID 36389387, 2022).
Arthritis (1 paper, 2024). Inflammation of a joint. "We then analyzed data also after sample stratification according to the type of arthritis, and we found that PIM-3 was upregulated in PsA after six months of treatment." (PMID 38542097, 2024).
asthma (1 paper, 2012). "We could not establish any association of this SNP (PIM3) with asthma but observed a novel polymorphism, Glu363Lys in exon-V of α1AT upstream to PIM3, to be associated with bronchial asthma." (PMID 23226977, 2012).
brucellosis (1 paper, 2024). Brucellosis is a bacterial infection that spreads from animals to people via unpasteurized dairy products or by exposure to contaminated animal products or infected animals. "The expression levels of multiple genes (e.g., PIM1, PIM3, KLF4) involved in the ‘negative regulation of cell apoptotic process’ were higher in brucellosis patients than in controls." (PMID 39135683, 2024).